TRGV10 (T cell receptor gamma variable 10 (non-functional))
Description:
Probable non-functional open reading frame (ORF) of V region of the variable domain of T cell receptor (TR) gamma chain. Non-functional ORF generally cannot participate in the synthesis of a productive T cell receptor (TR) chain due to altered V-(D)-J or switch recombination and/or splicing site (at mRNA level) and/or conserved amino acid change (protein level). Gamma-delta TRs recognize a variety of self and foreign non-peptide antigens frequently expressed at the epithelial boundaries between the host and external environment, including endogenous lipids presented by MH-like protein CD1D and phosphoantigens presented by butyrophilin-like molecule BTN3A1. Upon antigen recognition induces rapid, innate-like immune responses involved in pathogen clearance and tissue repair. Binding of gamma-delta TR complex to antigen triggers phosphorylation of immunoreceptor tyrosine-based activation motifs (ITAMs) in the CD3 chains by the LCK and FYN kinases, allowing the recruitment, phosphorylation, and activation of ZAP70 that facilitates phosphorylation of the scaffolding proteins LCP2 and LAT. This lead to the formation of a supramolecular signalosome that recruits the phospholipase PLCG1, resulting in calcium mobilization and ERK activation, ultimately leading to T cell expansion and differentiation into effector cells. Gamma-delta TRs are produced through somatic rearrangement of a limited repertoire of variable (V), diversity (D), and joining (J) genes. The potential diversity of gamma-delta TRs is conferred by the unique ability to rearrange (D) genes in tandem and to utilize all three reading frames. The combinatorial diversity is considerably increased by the sequence exonuclease trimming and random nucleotide (N) region additions which occur during the V-(D)-J rearrangements.
Synonyms: V3P; TCRGV10
Gene: T-cell receptor variable (V) gene on chromosome 7 (38,299,810 to 38,300,280, reverse strand). Ensembl gene ENSG00000211694.
Subcellular location: Cell membrane
Gene Ontology:
Cellular component: plasma membrane
Homologues: Orthologues: macaque TRGV10 (81% identical). Paralogues in human: TRGV11 (42% identical), TRGV9 (31% identical), TRGV1 (23% identical), TRGV2 (23% identical), TRGV3 (23% identical), TRGV5 (23% identical), TRGV4 (22% identical), TRGV8 (22% identical).
Diseases named in the same sentence as TRGV10 in open-access papers:
TRGV10 is named in the same sentence as 3 diseases in open-access papers, as found by Europe PMC text mining. Sharing a sentence is not in itself a finding about the gene and the disease.
TRGV10 shares sentences with these, for which no sentence is quoted: tumor (2 papers); metastatic tumors (1); prostate tumors (1).